IL15 (interleukin 15)
Diseases named in the same sentence as IL15 in open-access papers (continued):
Sharing a sentence is not in itself a finding about the gene and the disease.
hepatocellular carcinoma (32 papers, 2018 to 2026). A malignant tumor that arises from hepatocytes. "For example, in 2021, Vδ1 T cells were engineered using a glypican-3–specific CAR and soluble IL-15 to combat hepatocellular carcinoma." (PMID 40148988, 2025). "For example, glypican-3–specific CAR Vδ1 T cells with co-expressed IL-15 demonstrated enhanced anti-tumor activity against hepatocellular carcinoma, showing robust expansion and in vivo efficacy." (PMID 40148988, 2025). "Anti-GPC-3 chimeric antigen receptor (CAR) T-cells, combined with soluble IL-15, have shown significant efficacy in preclinical mouse models of hepatocellular carcinoma (HCC), highlighting GPC-3’s therapeutic potential." (PMID 39404428, 2024). "CSF‐1, CCL2, and IL‐15 are found to enhance the clearance of macrophages on hepatocellular carcinoma (HCC) cells." (PMID 41427020, 2025). "Additionally, in HrasG12V‐mutated hepatocellular carcinoma (HCC), senescent HCC cells secrete SASP factors (such as CCL2, IL‐15 and CXCL1) that activate macrophages, neutrophils and NK cells, thereby mediating innate immunity and suppressing tumour progression." (PMID 39270064, 2024). "In hepatoma cell cultures, SASP factors, including CSF1, MCP1, CXCL1 and IL‐15, as well as adhesion molecules such as Icam1 and Vcam1, have been observed to attract a spectrum of immune cell types, encompassing macrophages, NK cells and neutrophils." (PMID 39270064, 2024). "This suggests that these IL-15+/+/TGFβR2−/− iNK cells could be functionally resistant to TGF-β-mediated suppression in hepatocellular carcinoma (HCC), where TGF-β plays a central suppressive role." (PMID 39260365, 2024). "For example, the hepatocellular carcinoma (HCC) microenvironment is devoid of interleukin (IL) 15 and 21, which are essential for the proper functioning of T-cells, therefore human GPC3-CAR T cells co-expressing IL-15 and IL-21 were very efficient in the treatment of HCC in preclinical models." (PMID 36428480, 2022). "Furthermore, using in vivo tumor models established by xenografting HepG2-hFAP, U87, and primary hepatic carcinoma cell lines into mice, we validated the antitumor efficacy of FAP/IL-15 CAR-T therapy." (PMID 41455698, 2025). "IL-15 could directly promote the anti-tumor activity of NK cells against HCC cell lines and hepatoma cells directly extracted from liver cancer tissues in vitro." (PMID 32075046, 2020). "However, a recent study of IL-15-expressing GPC3 CAR-T cells reported that infusion of those CAR-T cells into a patient with hepatocellular carcinoma (HCC) led to grade 4 cytokine release syndrome (CRS), which could be controlled by administration of rimiducid to trigger apoptosis of CAR-T cells." (PMID 37564658, 2023). "Meanwhile, the immunosuppressive function of LAMP3+ DCs has been validated in hepatocellular carcinoma (HCC) and non-small-cell-lung cancer (NSCLC) where LAMP3+ DCs showed strong interaction with exhausted T cells, Tregs and proliferating T cells via CD28/B7 binding and IL-15 signaling." (PMID 34568077, 2021). "Notably, constitutive co-expression of IL-15 with a glypican-3 CAR conferred greater intrinsic antitumor activity on human Vδ1+ cells in a hepatocellular carcinoma model—without inducing GvHD—highlighting the broadly beneficial role of IL-15 across innate-like platforms." (PMID 41583436, 2025).
multiple myeloma (32 papers, 2009 to 2026). "In this context, 2 key myeloma markers, MYC and DKK1, as well as many other cancer-associated genes, including ADM, HDGF, IL15, HGF, STMN1, CDKN1B and CD82, were potentially regulated by the predicted ligands." (PMID 41056512, 2025). "In conclusion, CAR-IL-15-pNK cells treated with ENT during ex vivo expansion demonstrated enhanced CAR and IL-15 expression, resulting in superior anti-myeloma activity in vivo." (PMID 40124378, 2025). "We also investigated the validity of our results in a multiple myeloma mouse model of MM1S treated with anti-CD70-CAR/IL-15 (CAR70/IL-15) NK cells." (PMID 38238616, 2024). "NK:TCR/IL-15 demonstrated a marked enhancement of TCR-mediated cytotoxicity as well as enhanced NK-mediated cytotoxicity resulting in improved persistence and performance of NK:BOB1-TCR/IL-15 cells in an orthotopic multiple myeloma mouse model." (PMID 38690288, 2024). "For the multiple myeloma (MM) model, a group found IL15 to be superior when they compared different combinations of IL-15 and IL-2 cytokines in B-cell maturation antigen (BCMA)-targeted CAR-T cells." (PMID 38201467, 2023). "Since IL-15 is also up-regulated in the sera of patients with multiple myeloma, it has been found that those malignant plasma cells expressed all three components of the IL-15R heterotrimer." (PMID 32929618, 2021). "In this study we demonstrated that promotion of NK cell accumulation in BM by CXCR3 targeting is critical for the long-lasting anti-myeloma response of IL-15 activated NK cells." (PMID 31699153, 2019). "CXCR3 inhibition increases BM infiltration of IL-15 activated cells, thus improving and prolonging their anti-myeloma effect up to 7 days." (PMID 31699153, 2019). "In our study, we demonstrated that NK cells activated with IL-2 and IL-15 were able to efficiently kill multiple myeloma cell lines and autologous myeloma cells." (PMID 30542346, 2018). "In preclinical studies, this cytokine exhibited potent antitumor activities against established tumors in animal models, showing that CD8+ T cells play a pivotal role in the anti-myeloma effect of IL-15 agonists." (PMID 27809856, 2016). "Gene expression profiling of B cells from M-protein-positive p80HT mice revealed aberrant expression of genes known to be important in the pathogenesis of multiple myeloma, including cyclin D1, cyclin D2, Blimp1, survivin, IL-10 and IL-15." (PMID 22642622, 2012). "Bcl-3 was induced in myeloma cell lines by interleukin (IL)-6, IL-21, IL-15, tumor necrosis factor-α and IGF-1, and its upregulation was associated with increased proliferation of the cells." (PMID 19191868, 2009). "Furthermore, both the NK-mediated as well as TCR-mediated cytotoxicity of the NK:TCR cells is enhanced, resulting in improved persistence and performance of NK:TCR/IL-15 cells in an orthotopic multiple myeloma mouse model." (PMID 38690288, 2024). "Thus, they are poorly effective in the short time frame, even upon deletion of Cxcr3 gene, but their anti-myeloma effect becomes important later after re-stimulation with IL-15." (PMID 31699153, 2019). "Despite the higher production of IFN-γ of CIK cells in the IL-15 mDCs (6 days) group compared to IL-15 mDCs (8 days) group, we did not observe a significant different with CD107a degranulation assay against both cancer cells line and autologous primary myeloma cells." (PMID 35413499, 2022). "Moreover, we correlated them with markers of myeloma activity, such as serum levels of IL-6, IL-10, IL-15, beta-2 microglobulin (B2M), and C-reactive protein (CRP), as well as with plasma cells' infiltration and Ki-67-PI in the bone marrow, both in diagnosis and after effective therapy." (PMID 23936794, 2013). "CAR27/IL-15 NK cells exerted potent in vitro and in vivo cytotoxicity against CD70+ multiple myeloma cells, comparable with CAR27/IL-15 T cells, and remained effective in BCMA knockout models." (PMID 41144785, 2026).
multiple myeloma (continued). "Third, we developed three different tumor mouse models; namely, Raji lymphoma treated with CAR19/IL-15 NK cells; MM1S multiple myeloma treated with CAR70/IL-15 NK cells and an ovarian SKOV3 cancer model treated with CAR-TROP2/IL-15 NK cells." (PMID 38238616, 2024). "Compared with IL-2 or IL-7, IL-15 was found to increase the persistence and efficacy of CAR T cells in multiple myeloma." (PMID 36618357, 2022). "A comparison of CAR-T cell expansion in the presence of IL-2, IL-15, or a combination of IL-15/IL-7, revealed that IL-15 best enhances CAR-T persistence and function in a mouse model of multiple myeloma." (PMID 35432319, 2022). "ALT-803, a fusion complex of IL15 and IL15RA receptor, exhibited a more substantial tumor-killing effect than native IL15 in preclinical models of myeloma through promoting the proliferation of CD8 memory T cells and inducing large amounts of IFN-γ." (PMID 33381115, 2020). "Chemotherapy induces SASP containing IL15RA and IL-15 in MM and increased expression of IL-15/IL15RA on the membrane of senescent myeloma cells." (PMID 32570952, 2020). "Moreover, we demonstrate the feasibility of targeting CD70 in myeloma using NK cells engineered with a chimeric antigen receptor (CAR) incorporating the CD70 cognate receptor CD27 and IL-15 (CAR27/IL-15)." (PMID 41144785, 2026). "We isolated CD14+ monocytes from peripheral blood from multiple myeloma (MM) patients, and induced immature DCs with granulocyte-macrophage colony-stimulating factor (GM-CSF) and IL-4 in the presence or absence of IL-15 for 4–6 days." (PMID 35413499, 2022). "IL-15 mDCs also showed higher stimulatory capacity regarding autologous T cells, a higher proportion of CD44+ and IFN-γ+ in CD4+ and CD8+ T cells, and higher cytotoxicity of T cells against cancer cell lines and patient autologous primary myeloma cells." (PMID 35413499, 2022). "The resulting IL-15 DCs (6 days) exhibited outstanding activation of autologous T cells, CIK cells, and NK cells, and demonstrated strong cytolytic activity against both myeloma cell lines and patient autologous primary myeloma cells." (PMID 35413499, 2022). "On the other hand, IL-12/15/18 activated cells display a longer capacity to restrain multiple myeloma growth in vivo compared to IL-15 activated cells, that seems independent of CXCR3 function due to reduced expression levels of this receptor." (PMID 31699153, 2019). "IL-15 and IL-15 super-agonist ALT803 exhibit capabilities to increase NK cell cytotoxicity in AML patients and other tumor models such as advanced solid tumors (NCT01946789), multiple myeloma (NCT02099539), relapsed hematologic malignancy (NCT01885897) and metastatic NSCLC (NCT02989844)." (PMID 32117199, 2019). "Notably, IL-15 mDCs showed very good stimulatory capacity for autologous CIK cells, a higher proportion of CD44+, IFN-γ+, granzyme B+, and NKG2D in CIK cells, and a higher cytotoxicity of CIK cells against cancer cell lines and patient autologous primary myeloma cells." (PMID 35413499, 2022). "In addition, TRAIL expression was significantly increased upon cytokine stimulation on myeloma patients' NK cells, which is in concordance with the results of previous reports demonstrating TRAIL upregulation and improved NK cell cytotoxicity upon IL-2 and/or IL-15 stimulation." (PMID 30542346, 2018). "Briefly, a single dose of ALT-803, but not IL-15 alone, eliminated well-established 5T33P and MOPC-315P myeloma cells from the bone marrow of tumor-bearing mice and prolonged survival in myeloma-bearing mice." (PMID 24896845, 2014). "Besides its increased potency and longer half-life compared with native IL-15, IL-15SA/IL-15RαSu-Fc was shown to induce innate memory CD8+ T cells capable of non-antigen–specific killing in murine myeloma models." (PMID 26910920, 2016).
vitiligo (32 papers, 2019 to 2025). Generalized well circumscribed patches of leukoderma that are generally distributed over symmetric body locations and is due to autoimmune destruction of melanocytes. "The study has demonstrated a higher serum level of IL-15 in vitiligo patients than in controls, highly associated with epidermal H2O2 content and the disease activity." (PMID 36119071, 2022). "Recent data linked the oxidative stress to an increased expression of IL-15 and IL-15Rα in the epidermis of vitiligo patients." (PMID 35884944, 2022). "One study showed that IL15 causes the expression of NKG2D in memory CD8 + T Cells in skin with vitiligo, triggering the production of IFNγ and TNFα." (PMID 35643735, 2022). "Moreover, key mediators such as interferon-γ (IFN-γ), C-X-C chemokine ligand 9 (CXCL9) and 10 (CXCL10), as well as interleukin-15 (IL-15) are also implicated in etiology of vitiligo." (PMID 35884944, 2022). "The IL-15/CD122 signaling axis has emerged as a promising therapeutic target in vitiligo due to its critical role in the maintenance and effector function of tissue-resident memory T (TRM) cells." (PMID 40791580, 2025). "For example, CD49a+ TRM cells—co-expressing CD103—are enriched in lesional vitiligo skin and display enhanced cytotoxicity, granzyme B/perforin production, and stronger IL-15 responsiveness." (PMID 40791580, 2025). "Studies have found that elevated levels of IL-15 in the serum of patients with vitiligo correlate with disease severity." (PMID 40136446, 2025). "In murine models of vitiligo, blockade of IL-15 or its receptor subunits, particularly CD122, leads to reduced TRM cell activity, suppression of IFN-γ signaling, and sustained repigmentation." (PMID 40791580, 2025). "Correlation analysis showed a positive relationship between IFN-γ, CXCL9, CXCL10, CXCL11, IL-6, and IL-15 in the plasma of patients with recurrent vitiligo." (PMID 39981245, 2025). "In the context of vitiligo, IL-15 has been shown to drive the activation of CD49a+CD103+CD8+ TRM cells enriched in lesional skin." (PMID 40791580, 2025). "Recent advances in TRM biology and IL-15 pathway modulation offer transformative potential for vitiligo management, warranting a systematic evaluation of therapeutic targeting strategies." (PMID 40791580, 2025). "Autoreactive Trms in vitiligo require IL-15 for their maintenance in the epidermis, and studies in mice revealed that blockade of IL-15 signaling removed the Trms from the skin, resulting in repigmentation even after a short course of treatment." (PMID 39817457, 2025). "The frequency of CD49a+CD103+CD8+ TRM cells secreting Prf1 and GzmB was increased in the vitiligo lesions of patients, suggesting that the production of IL-2 or IL-15 is enriched in the environment of vitiligo areas." (PMID 39193473, 2024). "IL-15 is believed to play a crucial role in the survival of T-cells in the skin of individuals with vitiligo." (PMID 39201060, 2024). "Blocking IL-15 signaling with an anti-CD122 antibody effectively halted disease progression in mice with established vitiligo." (PMID 39201060, 2024). "IL-15 expression was elevated in both the perilesional skins and blood circulation of individuals with vitiligo, indicating increased levels of locally-expressed and secreted IL-15 in these patients." (PMID 39201060, 2024). "Previous research has also concluded that keratinocyte expression of IL-15 was substantially elevated in vitiligo patients and was highly related to H2O2 levels." (PMID 37762802, 2023). "In vitiligo pathogenesis, the role of IL-15 is represented by modulating IL-17 release and sustaining T cell memory actions." (PMID 37762802, 2023). "IL-15 is an important cytokine in vitiligo pathogenesis due to its ability to generate and maintain signals of tissue-resident memory T cells (TRM)." (PMID 37275386, 2023). "The relevance of the IL-15 pathway is further evident from the promising results achieved through inhibition of IL-15 in a mouse model of vitiligo." (PMID 35884944, 2022).
vitiligo (continued). "IL-15 expression in the epidermis and serum of patients with vitiligo was significantly higher when compared with healthy controls, and highly correlated with H2O2 levels." (PMID 36154894, 2022). "IFN-γ operates through JAK-STAT pathway which is particularly relevant for development and maintenance of vitiligo, whereas IL-15 activates T-resident memory cells." (PMID 35884944, 2022). "Another important pathway is the IL-15 cytokine pathway which has recently emerged in the pathogenesis of vitiligo, particularly through its role in the regulation of TRM." (PMID 35884944, 2022). "Based on the demonstration that TRMs require IL15 for their differentiation, the interruption of the IL15 pathway using an anti-CD122 antibody caused reversal of depigmentation in mice with stable vitiligo." (PMID 35643735, 2022). "Collectively, these results suggest that MSA-specific CD8+ TRM is responsible for vitiligo homeostasis and IL-15 signaling is a potential therapeutic target." (PMID 35432377, 2022). "IL-15 blocking antibodies are now being explored as a potential durable therapy for vitiligo patients (NCT04338581)." (PMID 34012438, 2021). "IL-15 is an important cytokine in vitiligo pathogenesis thanks to its ability to regulate IL-17 levels and maintain signals of T cell memory (TRM)." (PMID 34768860, 2021). "Patients with vitiligo have significantly higher serum IL-15 levels compared to healthy controls, and this positively correlated to vitiligo disease severity." (PMID 34371735, 2021). "IL-15 serum levels are higher in vitiligo patients than in controls and show a positive correlation with the extent of the disease." (PMID 34768860, 2021). "Reliance of TRM on IL‐15 is substantiated by several studies, for example, melanocyte‐specific TRM cells cluster in high IL‐15 production sites like hair follicles in the vitiligo skin, and antibody blockade of IL‐15 signaling durably reverses depigmentation." (PMID 33200838, 2021). "Recent studies highlighted the role of IL-15 on resident memory T cells in vitiligo pathogenesis and the interest to inhibit this cytokine or its receptor in vitiligo." (PMID 33936032, 2021). "Blocking the IL-15 signaling with an anti-CD122 antibody improves the skin depigmentation in mice with established vitiligo." (PMID 33633737, 2020). "IL15 promotes development of skin resident memory T cells, and a recent studies in a vitiligo mouse model and human tissues revealed that the IL15 receptor is important for autoimmune memory in vitiligo." (PMID 33384688, 2020). "In line with this, another study reported an enrichment of IFN‐γ‐producing CD49a+ CD103+ CD8+ TRM cells in vitiligo lesions, with a rapid granzyme B and perforin production response upon IL‐15 stimulation." (PMID 31230406, 2019). "Based on the existed research on the pathogenesis of vitiligo, it was hypothesized in present study that IFN-γ, IFN-γ-regulated chemokines, IL-6 and IL-15 are associated with disease activity and also predictive biomarkers for disease recurrence in vitiligo." (PMID 39981245, 2025). "For example, antibody blockade of IL‐15 signaling has shown promise in durably reversing vitiligo, indicating that modulation of TRM cell activity through cytokine targeting could be an effective approach in managing these conditions." (PMID 40066223, 2025). "This makes IL-15 a potential target for the treatment of patients with vitiligo." (PMID 40136446, 2025). "Based on previous research, we propose a hypothesis that IFN-γ, CXCL9, CXCL10, CXCL11, IL-6, and IL-15 are involved in the recurrence of vitiligo and are interconnected." (PMID 39981245, 2025). "In vitiligo, oxidative stress activates NF-κB signaling, thus inducing the expression and trans-presentation of IL-15 in keratinocytes; this enhances the activation and expression of cytotoxic proteins in CD8+ cells by activating both the STAT3 and STAT5 pathways." (PMID 39201060, 2024).